HOXA5 (homeobox A5)
Diseases named in the same sentence as HOXA5 in open-access papers (continued):
Sharing a sentence is not in itself a finding about the gene and the disease.
mesothelioma (1 paper, 2014). A usually malignant and aggressive neoplasm of the mesothelium which is often associated with exposure to asbestos. "Mesothelioma cells express high levels of two HOX genes, HOXA4 and HOXA5; when HXR9 is added to block HOX activity, mesothelioma cells but not normal mesothelial cells undergo apoptosis." (PMID 25525461, 2014).
osteoporosis (1 paper, 2020). A condition of reduced bone mass, with decreased cortical thickness and a decrease in the number and size of the trabeculae of cancellous bone (but normal chemical composition), resulting in increased fracture incidence. "Here, we described that miR-19a-3p involved in aging-induced osteoporosis via regulating Hoxa5-mediated BMSCs differentiation." (PMID 33014522, 2020). "In this study, we identified that miR-19a-3p downregulated in the BMSCs of aged mice and humans and involves osteoporosis via promoting osteoblast differentiation from BMSCs by targeting Hoxa5." (PMID 33014522, 2020). "In conclusion, our study reveals the critical role of the lncRNA Xist/miR-19a-3p/Hoxa5 pathway in aging-induced osteogenic differentiation of BMSCs, indicating the potential therapeutic target for osteoporosis." (PMID 33014522, 2020). "In conclusion, our study clarified the Xist/miR-19a-3p/Hoxa5 in age-related BMSCs differentiation, and thus, might provide potential therapeutic approach for osteoporosis." (PMID 33014522, 2020).
pancreatic ductal adenocarcinoma (1 paper, 2022). An infiltrating adenocarcinoma that arises from the epithelial cells of the pancreas. "In the EWAS catalog, we found that aberrant DNA methylation in HOXA5 (including cg14013695) was associated with pancreatic ductal adenocarcinoma and gene expression in the liver." (PMID 35836279, 2022). "Likewise, EWAS have also found associations between aberrant DNA methylation in HOXA5 and pancreatic ductal adenocarcinoma, as well as gene expression in the liver." (PMID 35836279, 2022). "Several genes in the 500 kb vicinity of HOXA5 (i.e., HOXA3, HOXA9, HOXA7, HOXA1, EVX1) were also associated with high density lipoprotein (HDL) cholesterol efflux capacity, BMI, and pancreatic ductal adenocarcinoma." (PMID 35836279, 2022).
Pancytopenia (1 paper, 2019). An abnormal reduction in numbers of all blood cell types (red blood cells, white blood cells, and platelets). "HoxA9 is co-expressed with additional HoxA proteins, in particular HoxA5, HoxA7, and HoxA10, in immature hematopoietic populations, which likely accounts for the observation that HoxA9-/- mice manifest only mild pancytopenia." (PMID 31120998, 2019).
pulmonary hypertension (1 paper, 2015). Increased pressure within the pulmonary circulation due to lung or heart disorder. "Other studies noted dysregulated HoxA5 expression in mouse pulmonary EC linked with pulmonary hypertension, but its precise role in EC function was not investigated." (PMID 25821967, 2015).
respiratory distress syndrome (1 paper, 2012). "HOXA5−/− mice exhibit respiratory distress syndrome-like symptoms, and show decreased expression levels of lung surfactant-related proteins, suggesting that down-regulation of homeobox genes may be involved in the pathogenesis of VILI, and are intriguing subjects for the future study of lung injury." (PMID 23071521, 2012).
sarcoma (1 paper, 2011). A usually aggressive malignant neoplasm of the soft tissue or bone. "Indeed we found increased expression levels for RMS-markers (Myog, Myl4, Igf2, Prox1), a FS-gene (Vcan), and LS-related genes (Pparg, Myo1e, Hoxa5, Plau), which further established the MD-tumors as mixed sarcomas consisting of RMS, FS and LS-compartments." (PMID 21533183, 2011).
Sotos syndrome (1 paper, 2022). Sotos syndrome is a rare multisystemic genetic disorder characterized by a typical facial appearance, overgrowth of the body in early life with macrocephaly, and mild to severe intellectual disability. "In this study, we compared DNAm levels at HOXA5 CpGs in individuals with BOS, Kabuki, Weaver, and Sotos syndromes." (PMID 35361921, 2022). "In this study, we compared DNAm levels at eight of the 13 HOXA5 CpGs (within ~500 base pairs) in the BOS signature to DNAm values at those same sites in individuals with Kabuki, Weaver, and Sotos syndromes." (PMID 35361921, 2022).
thymic lymphomas (1 paper, 2016).
uterine corpus endometrioid adenocarcinoma (1 paper, 2025). "Their study demonstrated that HOXA5 expression is significantly associated with poor prognosis in uterine corpus endometrioid adenocarcinoma (p = 0.044; HR = 1.832)." (PMID 40805172, 2025).
Wilms tumor (1 paper, 2022). An embryonal neoplasm characterized by the presence of epithelial, mesenchymal, and blastema components. "Our DNAm studies in Wilms tumor tissues identified hypermethylation of HOXA5 CpG sites." (PMID 35361921, 2022).
tumor (106 papers, 2009 to 2025). "This study aimed to evaluate the prognostic potential of HOXA5 in EC and to explore its association with common tumor-related proteins." (PMID 40805172, 2025). "We further found that HOXA5 has been implicated in tumor suppression across various cancer types through its regulatory effects on key oncogenic and hormonal pathways." (PMID 40805172, 2025). "In gastric cancer, HOXA5 expression is significantly downregulated, and this reduction is associated with larger tumor size, advanced TNM stage, and poor survival outcomes, potentially through the modulation of p21, c-Myc, and Ki67." (PMID 40805172, 2025). "HOXA5 was significantly associated with oncogenic pathways, highlighting its role in tumor development." (PMID 41209012, 2025). "HOXA5 downregulation was significantly associated with an increased tumor size and advanced TNM stage." (PMID 39858044, 2025). "The expression of HOXA5 was upregulated in OSCC samples compared to non-tumor tissue and was associated with survival rates." (PMID 39057044, 2024). "Positive regulators such as Myc and HoxA5 are interesting as oncogenic Myc signaling is intricately linked to cancer progression and HoxA5 appears to be an important tumor suppressor." (PMID 36358595, 2022). "In CRC, HOXA5 is also down-regulated and its up-expression induces loss of the cancer stem cell phenotype, preventing tumor progression and metastasis." (PMID 34027794, 2021). "In CRC, HOXA5 is down-regulated and its expression induces loss of the cancer stem cell phenotype, preventing tumor progression and metastasis by inhibiting wnt signaling." (PMID 34027794, 2021). "For example, the loss of HOXA5 in breast cancer cells can promote tumor cells to differentiate in the direction of cancer stem cells, thereby promoting tumor progression." (PMID 34027794, 2021). "The study shows that HOXA5 loss in tumor cells causes reduced downstream target expression involved in maintaining epithelial integrity, which leads to a subsequent increase in invasion and migration." (PMID 33384715, 2020). "HOXA5 gene plays a role in lung organogenesis, digestive tract morphogenesis, thyroid and mammary glands development, ovary homeostasis and tumor predisposition and progression." (PMID 33225883, 2020). "Among these transcription factors was STAT3, which can have an oncogenic or tumor suppressor role depending on the mutational status of the tumor or the methylation status of the HoxA5 promoter, resulting in a loss of expression." (PMID 31040909, 2019). "HOXA5 methylation was associated with age, T, M, stage, and tumor status, and HOXA6 methylation was associated with age and KRAS mutation." (PMID 31165042, 2019). "Lower HOXA5 expression was associated with larger tumor size, advanced TNM stage and increased lymph node metastasis." (PMID 28423732, 2017). "Deregulated Hoxa5 expression is reported in cancers, indicating Hoxa5 involvement in tumor predisposition and progression." (PMID 29615582, 2016). "In contrast to the Hox3 genes, HoxA5 and HoxD10 are expressed in resting quiescent vessels, whereas expression is lost in tumor-associated vessels." (PMID 25821967, 2015). "HoxA5 expression can be attenuated by mir130a, which is induced by VEGF, as well as inflammatory factors which likely contribute to loss of endogenous HoxA5 in tumor-associated vasculature." (PMID 25821967, 2015). "Regression analysis (TCGA) confirmed significant associations between HOXA5 and tumor status." (PMID 41209012, 2025). "Therefore, this study aimed to evaluate the prognostic potential of HOXA5 in EC through immunohistochemical analysis of clinical tissue samples, and to explore its association with common tumor-related proteins." (PMID 40805172, 2025). "As GSCs are required for GBM tumor initiation and the main cause of tumor recurrence, HOXA5 enrichment may be a powerful diagnostic tool and a potential therapeutic target." (PMID 39858044, 2025).
tumor (continued). "Indeed, HOXA5 expression is increased in gliomas, which is associated with increased tumor aggressiveness." (PMID 37626900, 2023). "Furthermore, HOXA5 methylation was shown to be associated with age, stage, and tumour status, while HOXA6 methylation was linked to age and KRAS mutation." (PMID 35054365, 2022). "Deregulation of HOXA5 gene expression is involved in tumor predisposition and development where it may be modulated by epigenetic mechanisms." (PMID 33547267, 2021). "Because DNA damage repair is also associated tumor resistance to treatment, such as chemo- or radio-therapy, HOXA5 might also contribute to tumor resistance to treatments." (PMID 34485110, 2021). "Thus, either a gain or a loss of Hoxa5 gene expression may disrupt normal growth and differentiation programs causing neoplasia." (PMID 29615582, 2016). "For that reason, HOXA5 functions as a tumor suppressor gene in CRC and is repressed by MYC and Wnt signaling." (PMID 39858044, 2025). "Collectively, these results support a dual role for HOXA5 in promoting proliferation while restraining the tumor’s invasive and angiogenic capacity, potentially explaining the improved survival observed despite increased Ki-67 expression." (PMID 40805172, 2025). "As a developmental transcription factor, HOXA5 typically functions as a tumor suppressor in solid tumors." (PMID 41209012, 2025). "Single-cell analysis confirmed high HOXA5 expression in malignant cells, fibroblasts, and endothelial cells across cancers, suggesting its role in tumor progression." (PMID 41209012, 2025). "HOXA5 exhibited spatial co-localization with malignant cells and strong positive correlation with tumor cell content, concentrated within malignant subpopulations." (PMID 41209012, 2025). "Previous studies indicate that HOXA5 acts as a tumor suppressor by inhibiting proliferation and inducing apoptosis." (PMID 41209012, 2025). "HOXA5 exhibits a “dual personality” in pan-cancer: primarily tumor-suppressive in solid tumors but oncogenic in hematologic malignancies." (PMID 41209012, 2025). "HOXA5 has a “dual personality” in pan-cancer: it is mostly a tumor suppressor in solid tumors, but it is transformed into a tumor promoter in blood tumors." (PMID 41209012, 2025). "Examination of TCGA tumor/normal pairs confirmed significant HOXA5 dysregulation in BRCA, HNSC, and LUAD." (PMID 41209012, 2025). "Ki-67 remained an independent predictor of high HOXA5 expression (adjusted OR = 1.12, 95% CI: 1.03–1.19, p = 0.004), reinforcing its strong correlation with tumor proliferation." (PMID 40805172, 2025). "HOXA5 positively correlated with ESCA, HNSC, and PAAD tumor status (high expression increases cancer risk), and negatively correlated with BRCA, COAD, and LUAD status (low expression increases cancer risk)." (PMID 41209012, 2025). "Among the top of the list sorted by the smallest adjusted P values were five genes: ADHFE1, EYA4, FBLIM1, HOXA3, and HOXA5, all hypermethylated in all tumor groups." (PMID 40753397, 2025). "A plausible explanation lies in the broader regulation of the tumor microenvironment mediated by HOXA5." (PMID 40805172, 2025). "In our cohort, high HOXA5 expression was also linked to significantly lower levels of CD31 and fibronectin, suggesting impaired angiogenic and stromal support for tumor invasion." (PMID 40805172, 2025). "Tumor microenvironment (TME) assessment confirmed this: HOXA5 positively correlated with ImmuneScore/StromalScore in LUAD, LUSC, LGG; negatively correlated in BLCA, KIRC." (PMID 41209012, 2025). "In non-small-cell lung cancer (NSCLC), reduced HOXA5 expression correlates with larger tumor size, lymph node metastasis, and worse outcomes, partially through p21-mediated growth inhibition." (PMID 40805172, 2025). "Beyond EC, HOXA5 has been studied extensively in a wide range of malignancies and is increasingly recognized as a key regulator of tumor suppression, differentiation, and prognosis." (PMID 40805172, 2025).
tumor (continued). "Mechanistically speaking, rs3094296 modulated the binding of TF HOXA5 in an allele-dependent manner to promote the expression of eRNA ENSR00000155786 and mRNA SENP7, which synergistically suppressed tumor cell proliferation." (PMID 38863031, 2024). "They concluded that alcohol intake is associated with methylation patterns at two CpG sites (cg03199996 and cg07382687) located in genomic regions associated with tumor suppressor activity (GSDMD and HOXA5 genes)." (PMID 39125744, 2024). "A dysregulated Sp1/miR-130b-3p/HOXA5 axis has been suggested to contribute to tumor angiogenesis and the progression of LIHC." (PMID 37240447, 2023). "HOXA5 inhibits the wingless (Wnt) signaling pathway, and aberrant HOXA5 expression affects tumor cell proliferation, differentiation, invasion, and apoptosis." (PMID 37834206, 2023). "Meanwhile, HOXA5 expression in the tumor tissues was verified using IHC staining and western blotting." (PMID 37845209, 2023). "Consistently, it was reported that the ectopic expression of HOXA5 suppressed proliferation and neoplasia in cervical cancer cells by repressing WNT signaling." (PMID 37626900, 2023). "We observed HOXA5 overexpression significantly impaired tumor sphere formation of PCa cells, while HOXA5 knockdown facilitated more tumor spheres." (PMID 37845209, 2023). "Silencing SPRY2 largely compromised the tumor-suppressive effect of HOXA5 in PCa progression and cancer stemness." (PMID 37845209, 2023). "Both the upregulation and downregulation of HOXA5 have been reported in a variety of malignant tumors, suggesting its role as a tumor suppressor and promoter." (PMID 37845209, 2023). "As a result, the weights of the tumors were lower in the group injected with HOXA5-overexpressed cells, whereas HOXA5 downregulation significantly promoted tumor growth." (PMID 37845209, 2023). "Meanwhile, our findings from subcutaneous and intracardiac xenograft tumor models indicated that HOXA5 upregulation was sufficient to reduce tumor sizes and distant metastases, thus supporting the tumor-suppressive role of HOXA5 in PCa progression." (PMID 37845209, 2023). "Our own patient cohort also confirmed that HOXA5 was a tumor suppressor, with similar tissue expression pattern and survival result." (PMID 36536414, 2022). "The expression of HOXA4 and HOXA5 in LUAD were negatively correlated with tumor purity and positively correlated with the infiltration of various immune cells such as B cells, T cells and macrophages." (PMID 35370463, 2022). "MXD1 overexpression inhibited the proliferation and tumor growth while MXD1 silencing abrogated the HOXA5-mediated proliferation inhibition." (PMID 36167790, 2022). "More importantly, MXD1 silencing abrogated the HOXA5-decreased proliferation and tumor growth of ECCA cells." (PMID 36167790, 2022). "The result of apoptosis analysis upon MXD1 overexpression was found conflicting with the anti-tumor effects of HOXA5." (PMID 36167790, 2022). "Based on the Ivy Glioblastoma Atlas Project data, HOXA5 was found to be abundant in peri-necrotic zones, pseudopalisading cells around necrosis and cellular tumor compared with other pathological areas (P <0.001)." (PMID 34485110, 2021).